SLC38A1 (solute carrier family 38 member 1)
Diseases named in the same sentence as SLC38A1 in open-access papers (continued):
Sharing a sentence is not in itself a finding about the gene and the disease.
tumor (37 papers, 2013 to 2025). "circ_000334, circ_006740, and circ_006371 are spliced from spermatogenesis-associated protein 6 (SPATA6), CUL3, and SLC38A1, which play an important role in tumor proliferation, migration, and apoptosis." (PMID 30349810, 2018). "Therefore, knockdown of NEAT1 suppressed CRC cells tumor growth and progression with the miR-138/SLC38A1 axis, exerting an underlying strategy for CRC management." (PMID 35676702, 2022). "Both SLC38A1 mRNA and protein expression were positively associated with clinicopathological characteristics (clinical stage, T stage, pathological grade, tumor size, and tumor thrombus), were negatively associated with survival, and were independent prognostic factors in HCC patients." (PMID 34697542, 2021). "Likewise, the glutamine transporter SLC38A1 is putatively associated with malignant transformation and tumor progression." (PMID 24712400, 2014). "The SLC38A1 downregulation can restrain tumor expansion and inhibit the migration of colorectal cancer cells." (PMID 39698464, 2024). "OTUD5 knockdown significantly reduced the IHC score of SLC38A1 in xenograft tumour tissues (P < 0.05)." (PMID 38658981, 2024). "Analogously, the expression of SLC38A1 in colorectal carcinoma is closely relevant to the clinical stage of tumor node metastasis (TNM)." (PMID 39698464, 2024). "The expression of solute carrier family 38 member 1 (SLC38A1) as a tumor-inducing agent has been found to be upregulated in CRC." (PMID 35676702, 2022). "SLC38A1 is an amino acid transporter, which is ubiquitous in tumor tissues, where it stimulates tumor cell proliferation, invasion, and migration." (PMID 35663198, 2022). "Compared to other predictive factors (age, sex, tumor pathological grade, clinical stage, T stage, N stage and M stage), the AUC for SLC38A1 expression was greater (AUC = 0.734)." (PMID 34697542, 2021). "Secondly, the specific relationship between SLC38A1 expression and tumor immune infiltration requires further investigation." (PMID 34697542, 2021). "Overexpression of SLC38A1 is related to tumor size, nodal metastasis, advanced tumor stage, Ki-67 expression, and ER status." (PMID 29562706, 2018). "Inhibiting SLC38A1 expression also reduced cell migration, providing evidence for increased cell migration as a mechanism for enhanced metastatic potential, and local invasiveness of SLC38A1-expressing tumor cells." (PMID 24712400, 2014). "SLC38A1, a glutamine transporter, plays a significant role in tumor cell migration and transport." (PMID 39388011, 2024). "Furthermore, research has revealed that SLC38A1 and SLC38A2 show increased expression levels in tumor cells, promoting tumorigenesis and closely associating with tumor cell proliferation and migration." (PMID 38358002, 2024). "Conversely to SLC38A3, upregulation of SLC38A1, SLC7A6, and SLC1A5 transporters in HCC tumors was associated with decreased overall patient survival, with SLC1A5 being the most significantly associated with tumor aggressiveness." (PMID 39062801, 2024). "Among those candidate genes, hsa_circ_0000396, which derived from exon 2 to 5 of solute carrier family 38 member 1 (SLC38A1) gene with a length of 522 nt, we designated as circSLC38A1, attracted our attention since SLC38A1 was essential for cell migration and tumor metastasis." (PMID 36697384, 2023). "Besides, when evaluating the impact of SLC1A5 and SLC38A1 on ferroptosis, different tumor types and heterogeneity should also be carefully considered." (PMID 36262284, 2022). "Moreover, the IHC staining results from 30 paired HCC tissues in our hospital further confirmed the significantly higher protein levels of SLC38A1 in tumor tissues (76.7% vs. 46.7%, p < 0.05)." (PMID 34697542, 2021). "In addition, we investigated the correlations between SLC38A1 expression and tumor-infiltrating immune cells (TIICs) or immune checkpoints." (PMID 34697542, 2021).
tumor (continued). "Additionally, SLC38A1 is essential for glutamine uptake in T cells, linking it to both immune and metabolic functions, making it a potentially interesting target for studying tumor immunity and therapeutic intervention." (PMID 40315269, 2025). "However, the roles of SLC1A5 and SLC38A1 in different tumor types are still under debate." (PMID 36262284, 2022). "Therefore, the functional complementarity between SLC1A5 and SLC38A1 is intertwined, and targeting both SLC1A5 and SLC38A1 could be further evaluated for their tumor suppression capability." (PMID 36262284, 2022). "Promoters of some genes with functions in amino acid transport (Slc7a11, Slc38a1, and Slc43a1) were occupied by ATF4 in DLD-1 MycER tumor cells." (PMID 40542844, 2025). "Disrupting Gln uptake via SLC1A5, SLC7A5, or SLC38A1 depletion, or by inhibiting GLS, enhances oxidative stress and curtails DNA damage repair, thereby sensitizing tumor cells to ionizing radiation." (PMID 40707944, 2025). "Glutamine is a nutrient used by tumor cells, and the uptake of glutamine depends on the expression levels of glutamine transporters SLC1A5 or SLC38A1 on the cell membrane." (PMID 40075587, 2025). "SLC38A1 is deubiquitinated and stabilized by OTUD5 and mediates the tumour-promoting role of OTUD5 in HCC." (PMID 38658981, 2024). "SLC38A1 is integral for YAP regulation of mTORC1; SLC38A1 is required for YAP1/TAZ-mediated mTORC1 activation and is critical for tumour formation, growth and progression in HCC." (PMID 38658981, 2024). "The increased expression of SLC38A1 correlated with AKT phosphorylation, which enhanced the proliferative potential of tumor cells." (PMID 39852119, 2024). "There are several glutamine exchangers (ASCTs and Na+-coupled neutral amino acid transporters (SNATs)) that are often overexpressed by tumor cells (e.g., ASCT2 — SLC1A5; SNAT1 — SLC38A1, SNAT2 — SLC38A, and SNAT5 — SLC38A5)." (PMID 35029792, 2021). "We used two independent patient cohorts, namely, a Cancer Genome Atlas (TCGA) cohort and a Clinical Proteomic Tumor Analysis Consortium (CPTAC) cohort, to analyze the role of SLC38A1 in HCC at the mRNA and protein levels, respectively." (PMID 34697542, 2021). "Thus, we considered that SLC38A1 may have a potential impact on tumor immunology." (PMID 34697542, 2021). "Univariate logistic regression analysis further showed that the upregulation of SLC38A1 expression in HCC was significantly correlated with high pathological grade, clinical stage, T stage, tumor differentiation, and tumor thrombus." (PMID 34697542, 2021). "The purpose of this study was to assess the expression of SLC38A1/SNAT1 in patients with OS, and further investigate the mechanisms by which it affects tumor growth and metastasis." (PMID 29108276, 2017). "In addition, GluOC increased the expression levels of the amino acid transporter SLC38A1, which promoted the TCA process by increasing the levels of α-KG, further promoting tumor growth and metastasis and inhibiting ferroptosis of TNBC." (PMID 40075587, 2025). "Another study showed that SLC38A1 activity in TNBC correlates with high levels of Ki-67 proliferative activity, lack of estrogen receptor expression, metastases to regional lymph nodes, significant tumor size, and late stages of the disease." (PMID 39852119, 2024). "Our analyses demonstrated that the mRNA expression of SLC38A1 in the tumor group was significantly higher than that in the nontumor group." (PMID 34697542, 2021). "Our results showed that both the mRNA and protein expression of SLC38A1 was upregulated in tumor samples when compared to adjacent nontumor samples." (PMID 34697542, 2021). "Strikingly, strong immunoreactivity for p-4EBP1 and SLC38A1 proteins was detected in most tumor tissues when compared with corresponding non-tumorous surrounding liver tissues." (PMID 29088718, 2017).
tumor (continued). "In addition, tumor tissues were analyzed using immunohistochemistry, and these results showed that GluOC reduced the expression levels of PTEN but increased the expression levels of P-PIK3CA, P-AKT, Nrf2, SLC7A11, GPX4, and SLC38A1." (PMID 40075587, 2025). "Using patient-derived tumor and adjacent non-cancerous tissues, we found that expression of the SLC1A5, SLC7A5, and SLC38A1, and NUPR1 is a rescue mechanism induced by GLS inhibition." (PMID 40707944, 2025). "Using patient-derived tumor and adjacent non-cancerous tissues, we confirmed that expression of the SLC1A5, SLC7A5, and SLC38A1 is a rescue mechanism induced by GLS inhibition." (PMID 40707944, 2025). "In contrast, the one-carbon metabolism-related gene SLC38A1 was significantly more downregulated in MSI tumors compared to MSS (MSI: FC = −1.59, 95% CI −1.91 to −1.33 vs. MSS: FC = −1.05, 95% CI −1.17 to −1.06; ANOVA interaction p = 2.2 × 10−4), independent of tumor location." (PMID 41440189, 2025).
infection (6 papers, 2011 to 2024). The state of being infected such as from the introduction of a foreign agent such as serum, vaccine, antigenic substance or organism. "Taken together, these data suggest SLC38A1 might inhibit D. nodosus and/or F. necrophorum by limiting glutamine nutrient availability, either before or during infection." (PMID 38288162, 2023). "To explore whether the uptake of exogenous serine is mediated by the amino transporter, we depleted SLC38A1 by using shRNAs in CD34+ cells via lentiviral infection, leading to the increase of serine levels in the conditioned medium (CM) from cells with SLC38A1 knockdown." (PMID 37055385, 2023). "Several genes, such as cadherin-like molecule 26 (CDH26), nebulin (NEB), deiodinase, iodothyronine, type II (DIO2), and solute carrier family 38, member 1 (SLC38A1), were significantly up-regulated during both the primary infection and reinfection." (PMID 21414188, 2011). "PoRVA infection increased the mRNA levels of SLC1A5 and SLC38A1, but did not affect the mRNA levels of other glutamine transporters." (PMID 38905309, 2024).
metabolic disorders (2 papers, 2025). "Importantly, several of these genes (e.g., IRF2, SLC38A1, CLEC2D) have been previously implicated as potential biomarkers or functional mediators in autoimmune or metabolic disorders, supporting their relevance for early detection strategies." (PMID 40740938, 2025).
adenocarcinoma (1 paper, 2016). A common cancer characterized by the presence of malignant glandular cells. "We assessed the expression of Na+-solute co-transporters, members of the SLC5 family and the Na+-driven glutamine transporters SLC38A1 and SLC38A2, in human NSCLC (adenocarcinoma) samples compared to normal lung tissue using a large, public dataset published at GEO (GDS3257)." (PMID 27294516, 2016).
digestive system neoplasm (1 paper, 2021). A neoplasm (disease) that involves the digestive system. "The results showed that inhibiting SLC38A1 suppressed the cell viability and migration of Eca109 and KYSE-150 cells, which further proved the carcinogenic role of SLC38A1 in digestive-system neoplasms." (PMID 34291083, 2021).
hematologic tumors (1 paper, 2024). "Interestingly, the expression levels of most FRGs, including SLC38A1, SLC11A2, and HMOX1, were found to be lower in CML samples compared to other types of hematologic tumors." (PMID 39026664, 2024).
neurodegenerative disease (1 paper, 2022). A disorder of the central nervous system characterized by gradual and progressive loss of neural tissue and neurologic function. "CHMP5 has not been reported in previous ALS related research, and SLC38A1 is a main transporter of glutamine and has been reported as a positive regulator of mTOR complex 1 (mTORC1), which is closely connected with autophagy and plays an essential role in many neurodegenerative diseases." (PMID 35873477, 2022).
SLC38A1 also shares sentences with these, for which no sentence is quoted: Rett syndrome (5 papers); ovarian carcinoma (4); colorectal cancer (3); lymph node metastasis (3); breast tumors (2); cholangiocarcinoma (2); hilar cholangiocarcinoma (2); metastatic tumor (2); triple-negative breast carcinoma (2); acute pancreatitis (1); AIDS (1); Alcoholic Steatohepatitis (1); autism spectrum disorder (1); bladder cancer (1); breast adenocarcinoma (1); cerebral infarction (1); colon cancer (1); depression (1); diabetes (1); dwarfism (1); endometrioid carcinoma (1); esophageal cancer (1); esophageal squamous cell carcinoma (1); fibrosarcoma (1); folate deficiency (1); glioblastoma (1); HIV-1 infection (1); Hyperinsulinemia (1); ischemia (1); ischemic stroke (1).
A further 12 diseases each share a sentence with SLC38A1 in 1 paper.